IL1B (interleukin 1 beta)
Diseases named in the same sentence as IL1B in open-access papers (continued):
Sharing a sentence is not in itself a finding about the gene and the disease.
Parkinson disease (continued). "Biopsies from colon mucosa of subjects with Parkinson’s disease were immunoreactive for iNOS as well as IL-1β in both epithelium and stroma." (PMID 38187473, 2023). "Previous studies confirmed that baclofen reduced TNF-α and IL-1β expression in the MPTP-induced Parkinson’s disease rat model." (PMID 37903976, 2023). "Owing to the dual effect of Parkinson’s disease and surgical trauma, Aβ accumulation can activate NLRP3 and upregulate the expression levels of IL-1β, IL-18, and Caspase-1 to cause inflammation." (PMID 37232753, 2023). "In Parkinson’s disease for example, a significant increase in the expression of IL-1β was shown in the substantia nigra and frontal cortex, compared to controls." (PMID 34709564, 2022). "Studies in Parkinson's disease have reported similar attenuation of the circulating levels of cytokines IL‐1b, IL‐6 and TNF‐a in LPS treated mice." (PMID 36426551, 2022). "NLRP3 promoted the secretion of IL-1β/18 and pyroptosis to rupture microglia to further release inflammatory factors in Parkinson’s disease." (PMID 34775541, 2022). "In a model of human vascular endothelial cells, CLZ decreased ASC and caspase-1, while in renal I/R, it suppressed caspase-1, and in Parkinson-diseased rats, it reduced IL-1β." (PMID 36127628, 2022). "NLRP3 inflammasome blockade significantly prevents α-syn-induced microglial activation and IL-1β production, preventing neuronal damage of midbrain DA neurons, ultimately improving the symptoms in patients with Parkinson’s disease." (PMID 36009120, 2022). "NLRP3 activation promotes the secretion of the inflammatory cytokine interleukin-1β/18 (IL-1β/18) and induces pyroptosis to rupture microglia to further release inflammatory factor in Parkinson’s disease." (PMID 34775541, 2022). "TNFα and IL-1β are also increased in exosomes from patients with Parkinson’s disease, which transmit pathological effects and induce motor impairment when injected to normal mice." (PMID 35911759, 2022). "Injection of miR-155-5p agomir increases TNF-α, IL-1β, and IL-6 amounts in the ventral midbrain of Parkinson’s disease mice." (PMID 33692340, 2021). "Consistently, Fyn kinase activity also enhances NF-κB p65 nuclear translocation, which correlates with IL-1β gene expression in a Parkinson’s disease model." (PMID 34863113, 2021). "From the list of proteins taking part in inflammation, IL-21, IL-22, IL-1B are important proteins that are involved in MS, Parkinson’s disease, and other viral-bacterial CNS infections." (PMID 33833673, 2021). "Levels of IL-1β in plasma have a positive correlation with the Hoehn and Yahr staging scale and Unified Parkinson’s disease Rating Scale (UPDRS) part III scores." (PMID 32792920, 2020). "In the rotenone induced Parkinson's disease rat model, not only the levels of IL-6, IL-1β, and TNF-α in striatum were improved, but the level of GABA, DA, NE, and 5-HT was significantly increasing when treatment with spermidine compared with model group." (PMID 32625082, 2020). "This suggests that microglia secrete, in particular, IL-6 at an early Parkinson stage, but probably also IL-1β." (PMID 33716638, 2020). "Both Il1b and Tnfa are reported to be elevated in the MPTP model of Parkinson's disease, and IFNAR1 deficiency was also shown to reverse these, although fold‐increases in these transcripts were relatively small and rather variable." (PMID 30680794, 2019). "In Parkinson's disease model immunohistochemistry also revealed colocalization of IL-1β with Iba-1 in CNS." (PMID 26090236, 2015). "More recently, tumor necrosis factor (TNF) and interleukin-1-beta (IL-1β) signaling pathways have been found to play a role in the pathogenesis of Alzheimer's and Parkinson's diseases." (PMID 22312330, 2012).
Parkinson disease (continued). "The excessive production, activation, and release of IL‐1β, IL‐18, and GSDMD have been implicated in the development and progression of numerous autoimmune and inflammatory conditions, including RA, IBD, Parkinson's disease (PD), Alzheimer's disease (AD), and MS." (PMID 40686254, 2025). "Similarly, citronellol demonstrated suppression of TNF-α, IL-1β, and IL-6 in a Parkinson’s disease model, indicating a direct action in disrupting the NF-κB-mediated inflammatory cascade." (PMID 40656940, 2025). "Mendelian randomization suggests that altering the expression of the NLRP3-inflammasome, IL-1β or IL-18, does not affect Parkinson's disease risk or progression." (PMID 37886468, 2024). "Pathogenic protein aggregates, such as α-synuclein, initiate NLRP3 activation in the microglial cells, activating ASC, caspase-1, and the secretion of proinflammatory cytokines IL-1β and IL-18, and then contribute to the disease progression of Parkinson’s disease." (PMID 36231090, 2022). "Additionally, the miR-3473b targets the triggering receptor expressed on myeloid cells 2 (TREM2) and Unc-51 like autophagy activating kinase 1 (ULK1) to regulate the inflammatory response, such as the secretion of TNF-α and IL-1β, in Parkinson's disease." (PMID 36572876, 2022). "Moreover, a myriad of lncRNAs are known to be regulators of inflammatory signaling and neurodegenerative diseases, including IL-1β secretion and Parkinson’s disease." (PMID 34775541, 2022). "Moreover, a myriad of lncRNAs and miRs have been linked to the regulation of inflammatory signaling and neurodegenerative diseases, including IL-1β secretion and Parkinson’s disease." (PMID 34775541, 2022). "Similarly, DBS of the subthalamic nucleus revealed a reduced level of IL-1β in the substantia nigra of a rat model of Parkinson’s disease." (PMID 33514001, 2021). "Moreover, βHB can also suppress mRNA expression of the inflammatory cytokines TNF-α, IL-1β, and IL-6 in the microglia of a rat model of lipopolysaccharide-induced Parkinson’s disease." (PMID 29443873, 2018). "Aggregated α-synuclein in Parkinson’s disease could trigger IL-1β generation depending on the NLRP3 inflammasome in brain microglia." (PMID 28928639, 2017). "In contrary, studies on swimming mice for 4 weeks presented improvements in a model of Parkinson disease when assessed depressive-like behavior, locomotor behavior and long-term memory; accompanied with increased levels of interleukin 1-beta and of reactive oxygen species." (PMID 26690877, 2015). "Furthermore, it has recently been shown that systemic IL-1β exacerbates neurodegeneration and motor symptoms in a rat model of Parkinson's disease." (PMID 18801476, 2009). "The research hypothesizes that CTE can modulate key biomarkers involved in Parkinson’s pathology, including α-synuclein, interleukin-1β (IL-1β), and tumor necrosis factor-α (TNF-α), assessed through qRT-PCR, as well as interleukin-6 (IL-6) and TNF-α, evaluated through ELISA." (PMID 39642134, 2024). "Collectively, our data suggest that long-term exposure to increased IL-1β/IL-1α could evoke parkinsonism-related outcomes such as impairment in motor skills, a higher number of activated microglia, and reduced number of TH-neurons as described in IL-1ra−/− mice." (PMID 27356916, 2017). "In a rat model of toxin-induced Parkinson disease (PD) induced by 6-hydroxydopamine, persistent systemic inflammation induced by IL-1β resulted in a reduction in the number of neurons, as well as an increase in activated microglia in the substantia nigra (SN)." (PMID 25698933, 2015). "The obtained results reinforce the existing clinical evidence that Alzheimer's and Parkinson's diseases are accompanied by an inflammatory response, with considerably higher blood levels observed for pro-inflammatory cytokines: IL-6, TNF-α and IL-1β." (PMID 39751856, 2024).
Parkinson disease (continued). "For example, administration of naturally derived polyphenol chlorogenic acid reduced neuroinflammation by inhibiting NF-кB activation as well as diminishing IL-1β and TNF-α secretion in a MPTP-mouse model of Parkinson’s disease." (PMID 38283356, 2023). "Immunomodulatory effects on the increased levels of pro-inflammatory cytokines (e.g., TNF-α, IL-1β, and IFN-γ) have been observed in the Parkinson’s patient brains with a large number of proliferating activated immune cells." (PMID 37833807, 2023). "In a mouse model of Parkinson’s disease, metformin (150 mg/kg) reduced the amount of microglia, proinflammatory cytokines (TNF-α, IL-1β, and IL-6), and inducible nitric oxide synthase (iNOS)." (PMID 37759689, 2023). "Several studies observed that physical training downregulated the expression of some pro-inflammatory cytokines (IL-1β, IL-18, TNF-α) and improved cognitive performance in different models of Alzheimer’s and Parkinson’s diseases, as well as patients." (PMID 36361978, 2022). "A clinical study collected serum samples from 12 untreated patients with Parkinson’s disease (aged 63–78 years) and detected a significantly upregulated expression of NLRP3 inflammasome, caspase-1, and IL-1β levels." (PMID 36009120, 2022). "In the mouse model of fibrillar α-synuclein of Parkinson’s disease, the NLRP3 inflammasome of microglia is activated, resulting in the extracellular release of IL-1β." (PMID 36231090, 2022). "DA has been shown to block canonical NLRP3 inflammasome activation and IL-1β secretion induced by various stimuli in mouse microglia and in the MPTP parkinsonism model in vivo, though α-syn-mediated inflammasome activation was not tested." (PMID 35172843, 2022). "In mouse models of Parkinson’s disease, the downregulation of miR-30e, miR-190, and miR-7 enables NLRP3 and ASC expression, the cleavage of caspase-1, the release of IL-1β and IL-18 cytokines, and the cell death by pyroptosis." (PMID 34829842, 2021). "It is also worth noticing that chlorogenic acid attenuated the extensive release of release of TNF-α and IL-1β in the substantia nigra of the LPS-injected mice suggesting that this compound may suppress inflammatory response or damage in neurodegenerative diseases including Parkinson’s disease." (PMID 33374338, 2020). "There are a set of pro-inflammatory cytokines including IL-6, TNF, IL-1β, and IFN-γ in the serum of patients with Parkinson's disease." (PMID 32983119, 2020). "The study hypothesized that SHE possesses antioxidants that could mitigate Parkinson’s symptoms by influencing α-synuclein, acetylcholinesterase (AChE), TNF-α, and IL-1β." (PMID 38551975, 2024). "MLT also attenuated neuroinflammation in the 1-methyl-4-phenyl-1,2,3,6-tetrahydropyridine (MPTP)-induced model of Parkinson’s disease through the suppression of microglial activation, downregulation of the NLRP3 inflammasome components, and inhibition of IL-1β secretion." (PMID 36747075, 2023). "Evidence suggests that overexpression hsa-miR-1277 could ameliorate IL-1β-induced CHON-001 cell injury and inhibit the progression of Parkinson’s disease, but these studies were all in vitro." (PMID 37312153, 2023). "In a mouse model of Parkinson’s disease (PD), 6-shogaol counteracted the decreases of occludin and ZO-1 proteins and reduced the production of tumor necrosis factor-alpha (TNF-α) and IL-1β in the colon, thereby preventing inflammation-induced gastrointestinal dysfunction." (PMID 36355111, 2022). "Also, in a mouse model of Parkinson's disease, MET reduced the numbers of microglia and proinflammatory cytokines TNF‐α, IL‐1β, IL‐6, and iNOS." (PMID 33443781, 2021). "Exogenous administration of several miRNAs (miR-30e, miR-190, miR-7) to Parkinson’s disease mice models inhibits NLRP3, ASC, and caspase-1 expression, impairing the release of IL-1β and IL-18, limiting pyroptosis and, consequently, neuroinflammation and neuronal damage." (PMID 34829842, 2021).
Parkinson disease (continued). "Increased IL-1β levels after TBI may elicit basal ganglia dysfunction and parkinsonism-related outcomes that can be reversed by IL-1β neutralization." (PMID 31936248, 2020). "The authors reported higher levels of the proinflammatory cytokines IL-1β and MCP-1 in patients with Parkinson's compared to the control group and a reduction in the levels of these proinflammatory cytokines after an aquatic physiotherapy program for 1 month, two times a week (60 min/session)." (PMID 33293946, 2020). "Furthermore, PYC shows neuroprotective effects through antioxidant and anti-inflammatory potency, in traumatic brain injury and Parkinsonism mouse models and inhibited the upregulation of TNF-α, IL-6 and IL-1β." (PMID 26367267, 2015). "Indeed, overexpressing hsa-miR-1277 may reduce IL-1β-induced CHON-001 cell damage and slow the course of Parkinson’s disease." (PMID 38999923, 2024). "The mRNA expression and protein expression of inflammatory factors (TNF-α, IL-6 and IL-1β) in the substantia nigra were respectively measured by RT-qPCR and ELISA to assess the effect of elevated miR-375 in inflammatory response of 6-OHDA-induced Parkinson’s disease rats." (PMID 31927536, 2020). "Second, although previous studies have reported elevated levels of pro-inflammatory cytokines such as TNF-α, IL-1β, and IL-6 in the CSF of MSA patients compared to those with Parkinson’s disease, we did not detect similar cytokine increases in our mouse model." (PMID 40336104, 2025). "No cytokine was a specific marker for parkinsonism, but TNF-α, CPP, IL-1β, IL-4, and IL-6 may be useful for early differentiation of atypical parkinsonism to PD." (PMID 30390673, 2018). "Furthermore, via the activation of inflammasomes, especially NLRP3, the secretion of pro-inflammatory cytokines, such as IL-18 and IL-1β, are stimulated by α-SYN aggregates, a fact that establishes a negative correlation with the development of Parkinson’s disease." (PMID 39861194, 2025).
mastitis (144 papers, 2009 to 2026). Inflammation of breast tissue during lactation or postpartum due to an obstructed duct or infection. "Studies have shown that mastitis pathogenesis involves LPS and pathogenic microorganisms stimulating the release of pro-inflammatory cytokines such as IL-1β and TNF-α, leading to inflammatory damage in mammary tissues and marked increases in SCC." (PMID 40901059, 2025). "In the mouse mastitis model, mastitis was associated with upregulated IL‐6, TNFα, and IL‐1β levels in the bloodstream, immune cell aggregation in the colon, disintegration of TJ, and poorly aligned intestinal villi." (PMID 40552401, 2025). "The interaction between mint components and core targets shows that ursolic acid in mint is associated with TNF, IL–6, and IL–1β, reflecting its potential active role in the treatment of mastitis in dairy cows." (PMID 40005889, 2025). "Previous studies have shown that TNF-α, IL-1β, and IL-6 are closely related to mastitis pathogenesis, and expression of these three inflammatory cytokines are significantly increased in mastitis caused by S. aureus infection." (PMID 36947494, 2023). "Some strains of Staphylococcus aureus will induce mild and subclinical mastitis due to low production of cytokines IL-8 and IL-1β, while others will cause a higher production of these cytokines and hence clinical mastitis." (PMID 37016420, 2023). "Genome-wide association analyses have previously identified an association between this type of collagen with Interleukin 1 beta (IL-1β) secretion in African Americans following smallpox vaccination and resistance to clinical mastitis in cattle." (PMID 33324693, 2020). "Studies in primary cell cultures of BME cells obtained from high or low mastitis-resistant heifers challenged with heat-inactivated E. coli showed higher expression levels of IL1β and IL8 in resistant animals when compared with susceptible cows." (PMID 32182886, 2020). "More interestingly, a strain of S. uberis that induced acute mastitis in vivo caused twofold and fourfold higher expression of IL-8 and IL-1β, respectively, in isolated MECs in vitro than a strain isolated from a case of chronic mastitis." (PMID 26464939, 2014). "In clinical mastitis caused by S. aureus, IL-1β and TNF-α are expressed in the early stages of the infection period, soon followed by a considerable decrease." (PMID 24498088, 2014). "In addition, IFNG, IL–6, and IL–1β are also associated with at least two mint components, demonstrating that the treatment of mastitis in dairy cows with mint is the result of the synergistic action of multiple components." (PMID 40005889, 2025). "In this study, neutrophils in dairy cows with high mastitis risk may be stimulated by IL-1β or IL-8 in the blood, and the DNA conformation in the nucleus might be damaged by high ROS levels." (PMID 35572521, 2022). "Furthermore, methionine and arginine down-regulated the levels of TLR4 and IL1β in LPS-induced mastitis, which caused the excessive regulation of inflammatory changes, and thus damaged the cells." (PMID 32927884, 2020). "Previous studies have indicated that TNF, IL–6, and IL–1β, as pro–inflammatory factors, are highly expressed in cows with mastitis." (PMID 40005889, 2025). "Similar results have been found in Rendena cattle, an autochthonous Italian breed whose high expression levels of IL-1β in epithelial cells and leukocytes are related to mastitis resistance." (PMID 40302747, 2025). "Several studies have reported that the levels of TNF-α, IL-1β, IL-6, and IL-8 in dairy cows with mastitis increase." (PMID 40266913, 2025). "In other experimental studies involving mice and rats, during mastitis-induced episodes, increased levels of IL-1β, IL-6, TNF-α cytokines, and MPO were observed (see Section 4)." (PMID 41148692, 2025). "Disruption of the blood–milk barrier is also observed in mastitis, though IL-1β seems to be the key cytokine driving this adverse effect." (PMID 40564173, 2025).